FEZF1 (FEZ family zinc finger 1)
Description:
Transcription repressor. Involved in the axonal projection and proper termination of olfactory sensory neurons (OSN). Plays a role in rostro-caudal patterning of the diencephalon and in prethalamic formation. Expression is required in OSN to cell-autonomously regulate OSN axon projections. Regulates non-cell-autonomously the layer formation of the olfactory bulb development and the interneurons. May be required for correct rostral migration of the interneuron progenitors (By similarity).
Synonyms: FEZ; ZNF312B; HH22
Tractability: No criterion of Open Targets' tractability assessment is met for any kind of drug.
Gene: Protein-coding gene on chromosome 7 (122,301,303 to 122,310,691, reverse strand). Ensembl gene ENSG00000128610.
Subcellular location: Nucleus
Subcellular location (Human Protein Atlas): Nucleoplasm; Cytosol
Gene Ontology:
Molecular function: protein binding; DNA-binding transcription factor activity; RNA polymerase II cis-regulatory region sequence-specific DNA binding; DNA-binding transcription repressor activity, RNA polymerase II-specific; sequence-specific DNA binding; transcription cis-regulatory region binding
Biological process: regulation of transcription by RNA polymerase II; cell dedifferentiation; negative regulation of cell population proliferation; negative regulation of transcription by RNA polymerase II; positive regulation of DNA-templated transcription; regulation of neurogenesis; telencephalon development
Cellular component: nucleoplasm; nucleus
Genetic constraint (gnomAD): Loss-of-function variants: 8 observed, 34.38 expected, observed/expected ratio (o/e) 0.23, 90% interval 0.14 to 0.42. The upper end of that interval is the gene's LOEUF score, 0.42, which puts it in group 1 of 6, group 1 being the genes least tolerant of losing a copy. Missense variants: 546 observed, 642.23 expected, observed/expected ratio (o/e) 0.85, 90% interval 0.79 to 0.91. Synonymous variants: 259 observed, 279.4 expected, observed/expected ratio (o/e) 0.93, 90% interval 0.84 to 1.03.
Homologues: Orthologues: chimpanzee FEZF1 (99% identical), macaque FEZF1 (98% identical), pig FEZF1 (95% identical), rat Fezf1 (95% identical), mouse Fezf1 (94% identical), guinea pig FEZF1 (94% identical), rabbit FEZF1 (93% identical), tropical clawed frog fezf1 (72% identical), zebrafish fezf1 (60% identical). Paralogues in human: FEZF2 (52% identical), ZBTB49 (27% identical), BCL6 (18% identical), ZBTB7B (17% identical), ZNF683 (16% identical), BCL6B (16% identical), ZNF280D (16% identical), PRDM13 (15% identical), ZBTB14 (14% identical), ZNF280B (14% identical), ZBTB21 (14% identical), ZNF280C (13% identical), and 16 more.
Diseases named in the same sentence as FEZF1 in open-access papers:
FEZF1 is named in the same sentence as 26 diseases in open-access papers, as found by Europe PMC text mining. Sharing a sentence is not in itself a finding about the gene and the disease. The quoted sentences say what the papers report.
glioma (6 papers, 2019 to 2022). A benign or malignant brain and spinal cord tumor that arises from glial cells (astrocytes, oligodendrocytes, ependymal cells). "Other examples of the ceRNA-miRNA-mRNA axis in glioma include the lncRNA HOXA-AS3/miR-455-5p/USP3 axis, which promotes malignancy in GBM, and the Linc00152/miR-103a-3p/FEZF1 axis known to enhance malignancy in glioma stem cells (GSCs)." (PMID 36009578, 2022). "Up‐regulation of Linc00152 promotes malignant progression of glioma stem cells by regulating the miR‐103a‐3p/FEZF1/CDC25A pathway." (PMID 32307830, 2020). "In an in vitro experiment, FEZF1 promoted the proliferation, migration, and invasion of glioma cells and inhibited cell apoptosis by activating the protein kinase B alpha (Akt)-extracellular signal-regulated kinase (ERK) pathway." (PMID 31281667, 2019). "Moreover, miR-103a-3p inhibited malignant progression of glioma by binding to the FEZF1 3’-UTR." (PMID 35094292, 2022). "Interestingly, FEZF1 was shown to upregulate the expression of the oncogenic gene CDC25A, activating the PI3K/AKT pathway and promoting the malignant behavior of glioma stem cells." (PMID 34830820, 2021).
gastric cancer (4 papers, 2013 to 2018). A primary or metastatic malignant neoplasm involving the stomach. "FEZF1 (also known as ZNF312b) is a zinc finger transcriptional repressor that is an epigenetically-regulated oncogene in gastric cancer." (PMID 29113413, 2017). "By contrast, hyperacetylation in H3 of ZNF312b (FEZ family zinc finger 1) promotes the progression of gastric cancer." (PMID 24729878, 2014).
cervical cancer (3 papers, 2021 to 2023). A primary or metastatic malignant neoplasm involving the cervix. "FEZF1 promotes cell proliferation and migration by acting as a transcriptional activator of the Wnt signalling pathway and thereby plays an oncogenic role in cervical cancer." (PMID 37533239, 2023). "Thus, FEZF1 knockdown reduced cell proliferation and migration in human cervical cancer cell lines and was shown to be an independent predictive factor for recurrence in cervical cancer." (PMID 34830820, 2021). "FEZF1, which is a highly conserved transcription factor belonging to the C2H2 zinc finger protein family, has been shown to reduce cell proliferation and migration in human cervical cancer cell lines when it is knockdown and to act as an independent predictor of cervical cancer recurrence." (PMID 37035196, 2023).
Kallmann syndrome (3 papers, 2024 to 2025). Kallmann syndrome (KS) is a developmental genetic disorder characterized by the association of congenital hypogonadotropic hypogonadism (CHH) due to gonadotropin-releasing hormone (GnRH) deficiency, and anosmia or hyposmia (with hypoplasia or aplasia of the olfactory bulbs). "During development, Fezf1 is important for the correct penetration of axons through the olfactory plate, and mutations of this gene result in Kallmann syndrome, which is characterized by anosmia and hypogonadotropic hypogonadism." (PMID 41219904, 2025). "During development, Fezf1 neurons are involved in the organization of the olfactory bulb, and mutations on this gene are responsible for Kallmann syndrome; however, in adult life, little is known about the functions of Fezf1 neurons." (PMID 41219904, 2025). "Genetically, KS is featured in several disorders related to genes, with a high degree of genetic variation, and only approximately 40% of Kallmann syndrome is caused by known genetic mutations: KAL1 and FEZF1." (PMID 38635120, 2024).
Anxiety (1 paper, 2024). Intense feelings of nervousness, tension, or panic often arise in response to interpersonal stresses. "Within the ZNF family, FEZ zinc finger 1 (FEZF1), FEZ zinc finger 2 (FEZF2), ZNF, and FOG family member 1 (ZFPM1) contribute to the development and function of neural circuits, which are crucial for fear, anxiety, and behavioral regulation." (PMID 39595393, 2024).
autism (1 paper, 2019). Persistent deficits in social interaction and communication and interaction as well as a markedly restricted repertoire of activity and interest as well as repetitive patterns of behavior. "Therefore, FEZF1 was identified as a strong candidate gene for ASD in a family sequencing study and the region spans the autism susceptibly locus 1 (AUTS1)." (PMID 31651322, 2019).
bone sarcoma (1 paper, 2021). A sarcoma that arises from the bone. "This indicates that FEZF1 is highly expressed in Ewing sarcoma cells and that FEZF1 expression was specific for Ewing sarcoma, at least when compared to other bone sarcomas." (PMID 34830820, 2021). "We next compared the expression of FEZF1 in a panel of bone sarcoma cell lines, including Ewing sarcoma (n = 9), osteosarcoma (n = 3) and chondrosarcoma (n = 1)." (PMID 34830820, 2021). "FEZF1 was upregulated by EWSR1-FLI1 and was highly expressed in Ewing sarcoma cells when compared to other bone sarcomas and normal tissues." (PMID 34830820, 2021).
chondrosarcoma (1 paper, 2021). A malignant cartilaginous matrix-producing mesenchymal neoplasm arising from the bone and soft tissue. "FEZF1 expression was undetectable at the mRNA and protein level in osteosarcoma and chondrosarcoma cells." (PMID 34830820, 2021).
colorectal cancer (1 paper, 2019). A primary or metastatic malignant neoplasm that affects the colon or rectum. "In addition, FEZF1 promotes cell migration and invasion in colorectal cancer cells." (PMID 31281667, 2019).
lung adenocarcinoma (1 paper, 2023). A carcinoma that arises from the lung and is characterized by the presence of malignant glandular epithelial cells. "Among them, low expression of C12orf56, DLX5, DSC3, FEZF1, GSTA1, H2BC9, IGSF11 and high expression of EREG, CEACAM6, SLC34A2 in lung adenocarcinoma were found to predict poor prognosis for patients." (PMID 37035196, 2023).
lung squamous cell carcinoma (1 paper, 2023). "Ten prognostic beneficial factors of the heterogeneous expression of lung squamous cell carcinoma genes driven by TTN mutations were screened for and DLX5, FEZF1, H2BC9, EREG, and SLC34A2 were identified as the main factors of the prognostic models." (PMID 37035196, 2023).
malignant glioma (1 paper, 2022). A grade III or grade IV glioma arising from the central nervous system. "Mechanistically, LINC00152 binds to miR-103a-3p to suppress FEZ family zinc finger 1 (FEZF1), thereby promoting cell division cycle 25 A (CDC25A) expression to promote the PI3K/AKT pathway to exert these functions in malignant glioma." (PMID 36033524, 2022).
Obesity (1 paper, 2025). Accumulation of substantial excess body fat. "In female mice, the inhibition of BDNF in hypothalamic FezF1 neurons result in protection against diet-induced obesity due to a reduction in food intake and increased spontaneous ambulatory activity, whereas in males it leads to increased cold tolerance." (PMID 41219904, 2025). "The Fezf1-specific knockout of BDNF resulted in increased cold tolerance in males, and protection against diet-induced obesity due to a reduction in food intake and increased spontaneous ambulatory activity in females." (PMID 41219904, 2025).
cancer (3 papers, 2013 to 2022). A tumor composed of atypical neoplastic, often pleomorphic cells that invade other tissues. "Novel CISs that do not map near members of the canonical MMTV gene families, such as Myb and Fezf1, have been previously associated with cancer." (PMID 23690930, 2013). "FEZF1 is a critical transcription factor in nervous system development that has been recently involved in cancer progression." (PMID 34830820, 2021). "Beyond its role in brain development, little is known about the involvement of FEZF1 in disease, although some studies suggest a role of FEZF1 in cancer." (PMID 34830820, 2021). "As far as we know, this is the first time that a relationship between FEZF1 and Ewing sarcoma has been described and also one of the few times that FEZF1 has been studied in the cancer context." (PMID 34830820, 2021).
FEZF1 also shares sentences with these, for which no sentence is quoted: hypogonadotropic hypogonadism (2 papers); Anosmia (1); autism spectrum disorder (1); congenital hypogonadotropic hypogonadism (1); mammary tumors (1); multiple myeloma (1); Noonan syndrome (1); of puberty (1); osteosarcoma (1); pancreatic cancer (1); pancreatic ductal adenocarcinoma (1); prostate carcinoma (1).